BIRC3 (baculoviral IAP repeat containing 3)
Diseases named in the same sentence as BIRC3 in open-access papers (continued):
Sharing a sentence is not in itself a finding about the gene and the disease.
ovarian carcinoma (continued). "Our characterization of CRL4/BIRC3 axis provides new insights into mechanisms underlying ovarian cancer chemoresistance, and CRL4 may serve as a potential and novel therapeutic target for overcoming the bottle neck of ovarian cancer chemoresistance." (PMID 30718461, 2019). "Taken together, our results indicated that CRL4 and BIRC3 upregulation in ovarian cancer cells led to chemoresistance to cisplatin, suggesting that CRL4 and BIRC3 might serve as novel targets for relapsed patients after treatment with cisplatin and its derivatives." (PMID 30718461, 2019). "In support of an antitumor tumor immune response, by targeting intracellular PD-L1 with a cell-penetrating antibody, the mRNA expression of PDCD1LG2, BIRC3, RELB, and VSIR was significantly decreased in ovarian cancer cells." (PMID 39996786, 2025). "We also found a significant positive correlation between PD-L1 (CD274) and the PDCD1LG2, BIRC3, RELB, and VSIR genes in the TCGA ovarian cancer-patient database." (PMID 39996786, 2025). "Therefore, the indirect strategy for evasion of apoptosis might be the reduction in the functional caspases and/or an elevation in the level of antiapoptotic protein such as BIRC3, which is further strengthened in this current study in ovarian cancer background." (PMID 36899893, 2023). "We have shown that COL11A1 enhances Src/Akt/NFκB activation in human ovarian cancer cell lines, leading to upregulation of inhibitor of apoptosis protein (IAP) expression (BIRC2, BIRC3, XIAP)." (PMID 33668097, 2021). "We previously established that COL11A1 promotes cisplatin resistance in ovarian cancer cells through activation of NFkB and upregulation of specific inhibitors of apoptosis (IAPs; BIRC2, BIRC3, and XIAP)." (PMID 34638339, 2021). "Inducing apoptosis via silencing of SMYD3 has also been observed in ovarian cancer in vivo and has been accredited to the upregulation of CD40LG and downregulation of BIRC3." (PMID 33333978, 2020). "In summary, our findings reveal that downregulation of CRL4 is responsible for downregulation of BIRC3 in ovarian cancer and that CRL4 plays an important role in apoptosis and chemoresistance in ovarian cancer by targeting BIRC3." (PMID 30718461, 2019). "The difference of BIRC3 regulation by AKT pathway between lung cancer and ovarian cancer may be due to tissue specificity." (PMID 30718461, 2019). "There are limited data regarding the role of CRL4 in BIRC3 regulation, we first examined whether PI3K activity was required for BIRC3 expression in ovarian cancer." (PMID 30718461, 2019). "In another example, miR-142-5p targeted several antiapoptotic genes, including baculoviral IAP repeat-containing 3 (BIRC3), B-cell lymphoma-2 (BCL2), BCL2-like 2 (BCL2L2), and myeloid cell leukemia sequence 1 (MCL1), and could improve cisplatin-mediated anticancer function in ovarian cancer." (PMID 31861383, 2019). "Therefore, PI3K activity may not be a direct target of CRL4, thus is not responsible for the change of BIRC3 expression in ovarian cancer." (PMID 30718461, 2019). "Interestingly, this group did not see an induction of the pro-survival proteins BIRC2, BIRC3, nor Bcl-2 when COL11A1 was overexpressed in A2780 and ES2 ovarian cancer cell lines, nor a reduction of these proteins when COL11A1 expression was knocked down in A2780CP70 ovarian cancer cell line." (PMID 33668097, 2021).
prostate carcinoma (26 papers, 2008 to 2026). A carcinoma that arises from epithelial cells of the prostate gland. "BIRC3 is associated with chemotherapy resistance in Ewing sarcoma, rhabdomyosarcoma and prostatic cancer." (PMID 18959781, 2008). "TIMER was used for correlation analysis and it indicated that UBASH3B was significantly correlated with LCP2 (p = 3.37e-40, cor = 0.547), PIK3CG (p = 2.44e-38, cor = 0.536), and BIRC3 (p = 0, cor = 0.534) in prostate cancer." (PMID 32010618, 2019). "Upregulation of BIRC3 promoted prostate cancer development and inhibited NK cell activities." (PMID 33098370, 2020). "Moreover, LCP2, PIK3CG, and BIRC3 were also positively correlated with these six types of immune cells in prostate cancer." (PMID 32010618, 2019). "BIRC3 and PIM2 are recognized anti-apoptotic factors, and GSTM2 is a biomarker for the early stages of the prostate cancer." (PMID 34209090, 2021).
colorectal cancer (25 papers, 2011 to 2024). A primary or metastatic malignant neoplasm that affects the colon or rectum. "The methylation of five genes (AHCYL2, IL11RA, SEMA6D, BIRC3, and HADHB) was associated with tumors, and four genes (IL11RA, CHL1, SEMA6D, and BIRC3) were associated with colorectal cancer." (PMID 29507648, 2018). "Fusobacterium nucleatum promotes chemoresistance to 5-fluorouracil by positively regulating BIRC3 expression in colorectal cancer (#37)." (PMID 37760489, 2023). "F. nucleatum promotes chemoresistance by upregulating BIRC3 expression and modulating autophagy in colorectal cancer." (PMID 31993418, 2019). "Specific inhibition of BIRC3 has recently emerged as a treatment for the treatment of cancers including oral squamous cell carcinoma, colorectal cancers, and other malignancies." (PMID 27074575, 2017). "Scholars in China have demonstrated that Fusobacterium nucleatum could promote 5-Fu resistance by upregulating BIRC3 expression in colorectal cancer." (PMID 36212852, 2022). "Recent studies have established a correlation between Fusobacterium nucleatum (Fn) and the occurrence and development of colorectal cancer (CRC), particularly noting that Fn infection upregulates BIRC3 in CRC cells via the TLR4/NF-κB pathway." (PMID 39301019, 2024). "With YAP1 activation, BIRC3/5 and MYC are the downstream targets of YAP1 under specific conditions, such as in cystic kidney epithelium and colorectal cancer cells." (PMID 38730465, 2024). "Online databases Oncomine and GEPIA were used to compare the expression of IAPs (NAIP, BIRC2, BIRC3, XIAP, BIRC5/survivin, BIRC6 and BIRC7, no data on BIRC8 was available) between colorectal cancer and normal tissues." (PMID 32381104, 2020).
glioblastoma (24 papers, 2009 to 2025). The most malignant astrocytic tumor (WHO grade IV). "More recently, BIRC3 overexpression has been linked to enhanced self-renewal and stemness maintenance in glioblastoma cell lines and patient-derived glioblastoma cells." (PMID 38247819, 2024). "In BC, esophageal adenocarcinoma, and glioblastoma, BIRC3 is associated with treatment resistance." (PMID 35656090, 2022). "On the other hand, chromosomal amplification or overexpression of BIRC3 was observed in various tumors, including glioblastoma and renal cell, gastric or small- and non-small-cell lung carcinomas." (PMID 39598439, 2024). "BIRC3 is an upregulated gene, also verified in our analysis, in glioblastoma and leads to therapeutic resistance due to its critical role in the NF-κB signaling pathway." (PMID 37662846, 2023). "Of note, our data are in line with those showing that BV6 can sensitize glioblastoma cells to TMZ and that BIRC3/c-IAP2 up-regulation results in apoptosis evasion and therapeutic resistance in glioblastoma." (PMID 34298797, 2021). "A previous study reported that BIRC3 was a mediator of therapeutic resistance to standard chemotherapy and radiotherapy in glioblastoma." (PMID 34488754, 2021). "Consistently, DNA amplifications of Birc2 and Birc3 have been observed in mouse liver and human lung cancers, liver carcinoma, oral squamous cell carcinoma, medulloblastoma, glioblastoma, and pancreatic cancer." (PMID 22682366, 2012). "Inhibiting the E3 ubiquitin ligase activity of BIRC3 can increase tumor cell sensitivity to radiotherapy and chemotherapy, and developing BIRC3 inhibitors may offer a promising approach for treating glioblastoma." (PMID 39301019, 2024). "BIRC3 is a member of the inhibitors of apoptosis proteins (IAPs) that contributes to therapeutic resistance in NSCLC and glioblastoma." (PMID 39858622, 2025). "Consistent with previous studies, BIRC3 and RNF135 were all previously reported as oncogenes in glioma, while we first revealed that RNF185 may play a tumor suppressor role in glioblastoma." (PMID 35183197, 2022). "Our analysis of expression profiles from four independent glioblastoma datasets suggests that hypoxia may induce TREM1, TNFAIP3 and BIRC3 in the inflammatory compartment." (PMID 19536297, 2009). "However, considering the GBM intra-tumoral heterogeneity and BIRC3 regional expression, we then analyzed BIRC3 and BMP4 expression using the IVY Glioblastoma Atlas dataset that has RNA-Seq datasets from MRI-distinct GBM regions." (PMID 35008722, 2021).
MALT lymphoma (24 papers, 2009 to 2025). An indolent, extranodal type of non-Hodgkin lymphoma composed of small B-lymphocytes (centrocyte-like cells). "Beyond TNFAIP3 and MYD88 mutations, MALT lymphoma shows rare or no mutations in other members of NF-kB pathway such as CD79A, CD79B, CARD11, BIRC3, and TNFRSF11A, which are frequently seen in other B-cell lymphomas with constitutive NF-kB activation." (PMID 35008340, 2021). "The absence of translocations affecting the genes BCL10, MALT1, BIRC3, or FOXP1, as they are frequently seen in other types of MALT lymphomas, in six OAML analyzed by WGS is in line with published data." (PMID 32316399, 2020).
chronic lymphocytic leukemia (20 papers, 2012 to 2024). "For instance, BIRC3 genetic inactivation due to deletions or point mutations is consistently associated to shorter progression free survival and poor prognosis in chronic lymphocytic leukemia patients." (PMID 33413657, 2021). "In contrast to overexpression in some tumor types, BIRC3 is sometimes deleted or mutated in chronic lymphocytic leukemia (CLL) and other lymphoid malignancies, and alterations in BIRC3 have also been associated with treatment resistance." (PMID 29167558, 2017). "A previous study has indicated BIRC3 inactivation is consistently associated to shorter PFS and poor OS in chronic lymphocytic leukemia patients." (PMID 38280104, 2024). "Previously, a number of authors noted the deletion of the BIRC3 gene in hematological malignancies, in particular in chronic lymphocytic leukemia (CLL), as an unfavorable prognostic marker." (PMID 38139431, 2023). "By boosting NF-B nuclear translocation, BIRC3 can predict the course of chronic lymphocytic leukemia (CLL) and characterize therapy sensitivity." (PMID 35656090, 2022). "Mutations of the anti-apoptotic gene BIRC3 and splicing factor SF3B1 have correlated with fludarabine refractoriness in chronic lymphocytic leukemia/small lymphocytic lymphoma." (PMID 32197371, 2020). "In addition, BIRC3 is reported to improve the prognostication system in Chronic Lymphocytic Leukemia and hepatocellular carcinoma patients undergoing curative resection." (PMID 33552736, 2021). "BIRC3 is also a negative regulator of the non-canonical NF-κB signaling pathway and mutated primarily in patients with aggressive chronic lymphocytic leukemia." (PMID 28520763, 2017). "BIRC3 is monoallelically deleted in up to 80% of chronic lymphocytic leukemia (CLL) cases harboring del(11q)." (PMID 34244476, 2021). "BIRC3 encodes a ubiquitin ligase, and alternative cleavage and polyadenylation generates short (BIRC3-SU) and long (BIRC3-LU) 3′UTR mRNA isoforms, the latter of which is significantly upregulated in chronic lymphocytic leukemia (CLL) cells." (PMID 33898516, 2021).
pancreatic cancer (20 papers, 2003 to 2023). "In addition, overexpression of BIRC3 significantly correlated with resistance to several chemotherapeutic drugs, including 5-Fu, in pancreatic cancer cells." (PMID 30630498, 2019). "Amplification of BIRC3 has been reported in acute myeloid leukemia and pancreatic cancer." (PMID 26247464, 2015). "Meanwhile, they used multiple human pancreatic cancer cell lines and revealed that miR‐374b‐5p up‐regulation relieved the chemoresistance of pancreatic cancer cells to gemcitabine by targeting several antiapoptotic genes, such as BCL‐2, BIRC3 and XIAP." (PMID 30772950, 2019). "In addition to protein levels, NSD3 induces global H3K36 dimethylation in pancreatic cancer cells and influences the mRNA levels for genes including ADAM28, ADAM9, BIRC3, CXCL5, DUOX2, GABRP, ITGB6, and RAB11FIP1." (PMID 37062069, 2023).
lung carcinoma (19 papers, 2010 to 2026). "Furthermore, the lower BIRC3 mRNA expression was obviously associated with a better survival in patients with lung cancer in the Human Protein Atlas database." (PMID 34692492, 2021). "Overexpression of Pellino-1 (an E3 ubiquitin ligase) is dependent on the expression of BIRC3 in human lung cancer cells, resulting in increased cell survival and colony forming ability." (PMID 34925455, 2021). "BIRC3 upregulated by E6 oncoprotein confers resistance to cisplatin in human papillomavirus 16/18-infected lung cancer." (PMID 27344170, 2016).
glioma (17 papers, 2017 to 2025). A benign or malignant brain and spinal cord tumor that arises from glial cells (astrocytes, oligodendrocytes, ependymal cells). "Transcriptomic analyses of irradiated GBM cells and the TCGA database reveal that the cellular inhibitor of apoptosis protein 2 (cIAP2), encoded by the BIRC3 gene, is a potential survival factor for senescent glioma cells." (PMID 39972068, 2025). "At variance with what described in gliomas, BIRC3 genetic inactivation due to deletions and/or point mutations is a negative prognostic factor and one of the drivers of therapy-resistance insurgence in CLL patients." (PMID 33413657, 2021). "Overexpression of BIRC3 is associated with glioma progression and aggression and chronic and acute B cell lymphocytic leukemia; it is also a predictor of therapeutic resistance to treatment with irradiation, doxorubicin, and temozolomide." (PMID 29507648, 2018). "BIRC3 is a known target of the transcription factor NF-κB, which is associated with poor prognosis and apoptotic resistance in gliomas." (PMID 27074575, 2017). "It has been reported that BIRC3 is associated with a poor prognosis in gliomas." (PMID 33818013, 2021). "BIRC3 expression enhanced neurosphere formation in CT-2A cells as we had observed in the human glioma cell lines." (PMID 35008722, 2021). "In vivo mouse glioma models also point to a role for BIRC3 in promoting malignant progression of LGG towards HGG." (PMID 33413657, 2021). "On the contrary, the progression from low grade gliomas to high grade gliomas is accompanied by BIRC3 expression increase, which bears relevant prognostic consequences." (PMID 33413657, 2021). "We show that of the 8 known IAPs (excluding Survivin) BIRC3 has a unique role in facilitating glioma progression from low- to high-grade." (PMID 27074575, 2017). "Using a unique murine model of glioma, we show that overexpression of BIRC3 promotes higher grade glioma and significantly reduces tumor-free survival in mice." (PMID 27074575, 2017). "In glioma cell lines with inhibited NF-κB expression, BIRC3 expression is also inhibited and these cells are sensitive to TNF-α induced cell death." (PMID 27074575, 2017). "In low grade gliomas, median survival for BIRC3 overexpressors (N=153) was 26.7 months compared to 94.5 months for nonexpressors (N=364) (log rank test p= 0.009)." (PMID 27074575, 2017). "However, recently described multinucleated and giant cells that arise after radiation of GB demonstrate increased expression of BIRC3 among other prosurvival signals underscoring the importance of BIRC3 in the biology of high-grade glioma." (PMID 27074575, 2017). "Thus, BIRC3 may be a potential therapeutic target to mitigate the transition from low-grade to high-grade glioma." (PMID 27074575, 2017). "Of the 3 genes (BIRC3, RNF135 and RNF185) with both differential expression and prognostic significance, BIRC3 and RNF135 were all previously reported as oncogenes in glioma." (PMID 35183197, 2022). "Although these treatments have yet to be attempted in brain tumors, our results demonstrating BIRC3 as upregulated in HGG relative to LGG and its effect on promoting malignant progression in vivo highlights its potential as a therapeutic target in glioma." (PMID 27074575, 2017). "BIRC3, KLHL10 and RNF135 showed unfavorable biomarker performance in glioma samples, and only RNF185 may serve as a favorable marker." (PMID 35183197, 2022). "Expression of BIRC3 in a PDGFB-dependent murine model of glioma resulted in shorter-symptom free survival compared to controls and also resulted in a shift to a more malignant glioma phenotype." (PMID 27074575, 2017).
multiple myeloma (16 papers, 2011 to 2024). "BIRC2 (cIAP1) and BIRC3 are also frequently inactivated by copy number loss or by nonsense or frameshift mutations in multiple myeloma." (PMID 36119107, 2022). "The NFκB pathway was altered in 45% of HMCLs, mostly by inactivating TRAF3 (frame-shift, non-sense mutation, insertion or deletion) or BIRC2/BIRC3 (homozygous deletion) as previously reported in primary myeloma cells." (PMID 30545397, 2018). "Homozygous deletions of CYLD and BIRC3 (cIAP2) are found exclusively in multiple myeloma and are both linked to aberrant NF-κB signalling." (PMID 29089486, 2017). "Human mature B cell lymphomas, including multiple myeloma (MM), mantle cell lymphomas (MCL) or marginal zone lymphomas (MZL), frequently harbor mutations or deletions of TRAF2, TRAF3 or BIRC3 (a.k.a. cIAP2)." (PMID 37679334, 2023). "This suggests that the repressed expression of NFκB inhibitors like A20, CYLD, IκBα and BIRC3 is an important mechanism of myeloma cell survival, and confirms the central role of NFκB signalling in myeloma pathogenesis." (PMID 26015393, 2015). "The combination of these compounds leads to rapid activation of NFκB signalling and a subsequent induction of a negative feedback loop, mediated via NFκB regulators such as BIRC3, resulting in myeloma cell death." (PMID 26015393, 2015). "Our data indicate that increased expression of NFκB regulators have an anti-myeloma effect, and this is supported by the high frequency of inactivating mutations found in these regulators (BIRC3, Traf2/3 and CYLD) in myeloma patients." (PMID 26015393, 2015). "Deletions of NFκB-pathway modulating genes TNFAIP3, BIRC2/BIRC3, TRAF3 or CYLD were identified in 16.6, 4.8, 13.9 and 16.9% of Myeloma XI cases, respectively." (PMID 28584253, 2018). "A BIRC2/BIRC3 deletion activates non-canonical NF-κB signaling in multiple myeloma, whereas 11q22 amplification (containing cIAP locus) was associated with earlier onset of disease in cervical cancer." (PMID 27167336, 2016).
colon carcinoma (14 papers, 2010 to 2021). "The cellular inhibitor of apoptosis protein 2 (cIAP2/BIRC3) also upregulates and activates Rac1, and promotes cell migration and wound healing of human colon cancer Caco-2 cells in vitro." (PMID 32178475, 2020).